PSAP (prosaposin)
Diseases named in the same sentence as PSAP in open-access papers (continued):
Sharing a sentence is not in itself a finding about the gene and the disease.
breast cancer (continued). "Paradoxically, in breast cancer, PSAP secreted by mesenchymal stem cells may suppress metastasis while promoting primary tumor cell survival." (PMID 40801564, 2025). "Several studies have shown that prosaposin, a regulator of estrogen receptor alpha, promotes breast cancer growth and that IGFs play an important role in cancer development and specifically and increased IGF-2 production has been linked with cancer development and progression in many conditions." (PMID 39580456, 2024). "Moreover, low expression of PSA, PSAP, and ER, PR were the markers for exclusion of prostate origin, and breast cancer origin, respectively." (PMID 36779496, 2023). "PSAP is a secreted protein that is detectable in conditioned medium from breast cancer cell lines." (PMID 26341737, 2015). "Further investigation of clinical samples using qRT-PCR analysis of mRNA levels in 223 ER-positive primary breast cancers from patients who had recurrent metastatic disease and were treated with tamoxifen as a first-line therapy, revealed a high PSAP expression level for 182 out of 223 patients." (PMID 20132547, 2010). "Indeed, PSAP does appear to induce activation of p-AKT in breast cancer cells in vitro." (PMID 26341737, 2015). "PSAP upregulates ERα expression, enhances its nuclear translocation and transcriptional activity through MAPK signaling, and significantly accelerates breast cancer cell growth in vitro and in vivo." (PMID 40801564, 2025). "Analysis of TCGA breast cancer dataset showed there to be a weakly positive correlation between HOXC11 and PSAP mRNA only in the luminal B subtype (rs 0.24)." (PMID 26341737, 2015). "PSAP has been demonstrated to be overexpressed in conditioned media of estrogen receptor (ER)-positive MCF-7 and ER-negative MDA-MB-231 breast cancer cell lines as well as in a human SV40-transformed breast epithelial cells, HBL100." (PMID 20132547, 2010). "Independently, using Mass Spectrometry based-proteomic analyses and qRT-PCR for comparative analysis of non-metastatic primary breast cancer and lymph node metastases, PSAP was found to be significantly increased (2 fold) in lymph node metastasis." (PMID 20132547, 2010). "To this end we decided to explore whether or not PSAP can also activate AR in AI-resistant breast cancer cells in the presence of unconverted endogenous androgens." (PMID 26341737, 2015). "Importantly these findings open up the possibility of utilizing anti-androgens in the treatment of a specific subtype of breast cancer expressing high levels of AR and PSAP, which may not exhibit sustained response to endocrine therapy." (PMID 26341737, 2015). "In addition to breast cancer and PCa, in a comparative analysis of the secretomes of an immortalized pancreatic duct normal epithelial cell (HPDE) and a pancreatic ductal adenocarcinoma cell line (Panc1), PSAP expression in Panc1 was found to 11-fold higher than in the HPDE cell line." (PMID 20132547, 2010).
glioma (11 papers, 2019 to 2025). A benign or malignant brain and spinal cord tumor that arises from glial cells (astrocytes, oligodendrocytes, ependymal cells). "Glioma signaling was primarily associated with Pattern 2, encompassing pathways such as PSAP and PDGF, while incoming signals were characterized by VEGF, NCAM, and PDGF." (PMID 40630954, 2025). "For ovarian cancer, gliomas, glioblastoma, hepatocellular carcinoma, and fibrosarcoma, PSAP participates in key pathways but requires further validation as a biomarker." (PMID 40801564, 2025). "TLR4 inhibition blocks PSAP-driven proliferation in gliomas, and inhibiting the PSAP/TGF-β1/Smad axis suppresses invasive growth in glioblastoma, and modulating PSAP expression enhances CD8+ T-cell responses against pancreatic cancer." (PMID 40801564, 2025). "Studies have reported high PSAP expression in clinical glioma specimens, glioma-stem cells and cell-lines with PSAP expression and secretion highest in mesenchymal tumours, the most aggressive transcriptional subtype of GBM." (PMID 38212481, 2024). "In glioma specimens, stem cells and cell lines, PSAP has been found highly expressed even in the secreted form and the expression level seems to correlate with a poor clinical prognosis." (PMID 36359323, 2022). "Prosaposin (PSAP) is highly expressed and secreted in gliomas and can promote glioma invasion and epithelial–mesenchymal transitions." (PMID 35327982, 2022). "Previously, we showed that PSAP levels in GBM-EVs have a significant, positive correlation to in vitro GBM cell invasion and multiple studies have reported high PSAP expression in clinical glioma specimens, glioma-stem cells and cell-lines." (PMID 32635403, 2020). "Furthermore, other cells within the GRN and PSAP signaling pathways were regulated by glioma cells, M1 macrophages, M2 macrophages, and endothelial cells." (PMID 38824202, 2024). "Moreover, PSAP stimulates glioma cell proliferation in vitro and regulates tumorigenesis through the toll-like receptor 4 (TLR4) associated to the nuclear factor kappa-light-chain-enhancer of activated B cells (NF-κB) signaling pathway." (PMID 36359323, 2022). "Although gliomas rarely metastasise beyond the CNS, reduced PSAP levels in plasma-EVs might reflect a mechanism whereby PSAP is selectively retained by GBM tumours to promote growth and invasion in the brain." (PMID 32635403, 2020). "In addition, PSAP can act as a biomarker in a variety of cancers, including gliomas, gastric cancer (GC), colorectal cancer (CRC), gallbladder cancer (GBC), hepatocellular carcinoma (HCC), pancreatic ductal carcinoma (PDAC), malignant pleural mesothelioma (MPM), and fibrosarcoma." (PMID 40801564, 2025). "Furthermore, secretory prosaposin affects the progression of prostate, breast and glioma cancer." (PMID 38607042, 2024). "PSAP overexpression in gliomas activates TLR4/NF-κB signaling, driving inflammatory factor release and glioma stem cell growth." (PMID 40801564, 2025). "Myeloid/microglial cells can communicate with MAN1C1-expressing glioma cells via signals produced (SPP1, GRN, PSAP, HBEGF, LGALS9, WNT5A)." (PMID 39333557, 2024).
Alzheimer disease (8 papers, 2011 to 2026). A progressive, neurodegenerative disease characterized by loss of function and death of nerve cells in several areas of the brain leading to loss of cognitive function such as memory and language. "In Alzheimer's disease (AD) and Parkinson's disease (PD), PSAP shows altered expression patterns and pathological co-localization with amyloid aggregates." (PMID 41627451, 2026). "Although both PSAP and PGRN protein levels are decreased in the brains of patients with schizophrenia, in some reports both are increased in Alzheimer's disease." (PMID 41438692, 2026). "In T1DM, some of the terms annotated were related to myelin dysregulation (ARHGEF6, CNP, NADK2, PSAP, SLC25A12) and other neurological disorders, such as Alzheimer’s disease (i.e., POA2, APOC1, APOC3, CNP, GSK3B, PON1, PSAP, SELENBP1) or movement disorders." (PMID 39901093, 2025). "Interestingly, several transcriptome-wide significant and colocalized genes outside genome-wide significant GWAS loci point to biologically relevant pathways related to neurodevelopment and neurodegeneration (PICALM, a known Alzheimer disease gene, CAMSAP2, AGTPBP1, SETD1A, EPRS, PADI2 and PSAP)." (PMID 38811690, 2024).
atherosclerosis (7 papers, 2022 to 2025). A disease characterized by the build-up of fatty material and calcium deposition in the arterial wall resulting in partial or complete occlusion of the arterial lumen. "Transplantation of PSAP‐deficient bone marrow into low‐density lipoprotein receptor knockout mice decreases plaque inflammation in atherosclerosis." (PMID 37269057, 2023). "PSAP encodes for prosaposin, which is linked to mTOR signaling and its macrophage expression is reported in atherosclerosis-associated inflammation." (PMID 35860693, 2022). "Intriguingly, in atherosclerosis models, which is also a lipid‐induced chronic inflammatory condition, downregulation of PSAP secretion in macrophages contributes to vascular inflammation." (PMID 40692664, 2025). "PSAP modulates macrophage function and plaque stability in atherosclerosis through multidimensional mechanisms." (PMID 40801564, 2025). "Inhibition of PSAP may led to a reduction in atherosclerosis development and in plaque inflammation." (PMID 39483475, 2024). "Several proteins downregulated in eWAT, such as PADI2, PSAP, NCK1, and NPM1, with proven pro-inflammatory properties that are normally secreted into the extracellular space, have been linked to the progression of atherosclerosis." (PMID 38017481, 2023). "Additionally, researchers are starting to recognize the importance of PSAP in cardiovascular diseases like atherosclerosis, as it might influence the formation of plaques by impacting the function of macrophages." (PMID 40801564, 2025). "Integrating multi-omics technologies with live imaging to evaluate combined PSAP-targeting regimens (e.g., mTOR inhibitors with GPR37 agonists) for advanced plaque regression may pioneer new avenues for precision intervention in atherosclerosis." (PMID 40801564, 2025).
Krabbe disease (7 papers, 2008 to 2025). A lysosomal disorder that affects the white matter of the central and peripheral nervous systems. "Globoid cell leukodystrophy or Krabbe disease is an autosomal recessive disorder caused by biallelic pathogenic variants in GALC (MIM# 245200) or PSAP (MIM# 611722) that leads to the deficiency of the enzyme galactocerebrosidase, or its activator protein saposin." (PMID 37564735, 2023).
neuroblastoma (7 papers, 2013 to 2025). Neuroblastoma (NB) is the most common solid, extracranial childhood tumor. "In this study, we aim to elucidate the neuroprotective roles of PSAP and saposin C in PD by evaluating their effects on α-synuclein accumulation in human neuroblastoma cells." (PMID 36152140, 2022). "In addition, PSAP and its active peptide prosaptide (peptides containing the neurotrophic sequence of PSAP) induced an increase in ganglioside content in NS20Y neuroblastoma cells, further emphasizing the key role of PSAP in the function of the nervous system." (PMID 40801564, 2025). "In 1994, the peptide prosaposin (PSAP) and its fragment Saposin C (Sap C) were identified as neurotrophic factors using the neuroblastoma NS20 line and specific binding of radio‐labeled Sap C with a Kd of 19 pM was demonstrated (O'Brien, Carson, Seo, Hiraiwa, & Kishimoto, 1994)." (PMID 30260505, 2018). "The first cells used to demonstrate a protective potential of PSAP were mouse neuroblastoma NS20Y and human neuroblastoma SK‐N‐MC cells." (PMID 30260505, 2018). "However, PGRN does not appear to have a significant role in PSAP lysosomal trafficking in the biosynthetic pathway as neuroblastoma cells N2a lacking PGRN expression still traffic PSAP to lysosomes." (PMID 28541286, 2017).
Parkinson disease (7 papers, 2019 to 2026). A progressive degenerative disorder of the central nervous system characterized by loss of dopamine producing neurons in the substantia nigra and the presence of Lewy bodies in the substantia nigra and locus coeruleus. "Additionally, it remains unclear whether known Gaucher modifiers like prosaposin (PSAP) or LIMP2 (SCARB2) also play a role in patients with GBA1-associated parkinsonism." (PMID 31464647, 2019). "In Parkinson’s disease (PD), PSAP influences disease pathogenesis by affecting α-Syn levels and regulating GCase activity." (PMID 40801564, 2025). "Cathepsin D participates in prosaposin cleavage too, and, together with progranulin, participates in a lysosomal network involved in Parkinson’s." (PMID 38607042, 2024). "Furthermore, overexpression of PSAP counteracts experimental Parkinson’s disease and protects dopaminergic neurons from damage." (PMID 40801564, 2025). "GBA1 hydrolyzes glucosylceramide into ceramide and glucose in lysosomes, and a recent study showed that CTSB is activated by ceramides to promote PSAP cleavage to saposin C, a coactivator of GBA1 in lysosomes, and that this process is altered in Parkinson disease." (PMID 38911600, 2024).
glioblastoma (5 papers, 2020 to 2025). The most malignant astrocytic tumor (WHO grade IV). "High levels of PSAP were detected in glioblastoma patients and were associated with unfavorable outcome." (PMID 32354122, 2020). "Prosaposin (PSAP) conserved glycoprotein acts as a neurotropic factor in the glioblastoma environment." (PMID 32354122, 2020). "Still, no clear association of PSAP with prognosis has been described, except for glioblastoma." (PMID 36134447, 2022).
Parkinsonism (4 papers, 2019 to 2024). Characteristic neurologic anomaly resulting from degeneration of dopamine-generating cells in the substantia nigra, a region of the midbrain, characterized clinically by shaking, rigidity, slowness of movement and difficulty with walking and gait. "One study reported that variants affecting Saposin-D cause an AD form of parkinsonism (PARK24, OMIM# 619491) in three families and that PSAP intronic variants near the Saposin-D domain-coding exons are a risk factor for sporadic PD." (PMID 36875645, 2023).
prostatic adenocarcinoma (4 papers, 2014 to 2025). "Although it is more difficult to distinguish prostatic mucinous adenocarcinoma from invasive bladder adenocarcinoma in some cases (e.g., it may be positive for both PSAP), bladder adenocarcinomas are focally PSA- and PSAP-positive, whereas prostatic adenocarcinomas are diffusely positive." (PMID 40896436, 2025). "Immunohistochemistry was negative for CK20, CK5/6, PAX-8, TTF-1, PSA, and PIN4, but positive for PSAP and NKX3.1, consistent with mucin-producing prostate adenocarcinoma." (PMID 41293260, 2025). "The tumor presenting the highest NTR1 expression was a poorly differentiated prostatic adenocarcinoma (CK20−, CK7−, PSAp+, p63−, p504s+) without neuroendocrine differentiation (CgA-, synaptophysin-), Gleason 9, node-positive, T3, R0." (PMID 30959962, 2019). "Rectal adenocarcinoma, unlike prostatic adenocarcinoma, shows positive staining for b-catenin, caudal-related homeobox 2 (CDX2) and carcinoembryonic antigen(CEA) but negative staining for PSA, PSAP, P501S." (PMID 24555830, 2014).
Anxiety (3 papers, 2022 to 2025). Intense feelings of nervousness, tension, or panic often arise in response to interpersonal stresses. "Dopaminergic PSAP-deficient (cPSAPDAT) mice display hypolocomotion and depression/anxiety-like symptoms with mildly impaired dopaminergic neurotransmission, while serotonergic PSAP-deficient (cPSAPSERT) mice behave normally." (PMID 37726325, 2023). "Cingulate-PSAP-deficient mice exhibited increased anxiety-like behavior and impaired prepulse inhibition, as well as intact locomotion, working memory, and a depression-like state." (PMID 36233357, 2022). "PSAP deficiency was shown to result in reduced movement, depression/anxiety-like symptoms, and mild impairment of dopaminergic neurotransmission in a mouse model in which PSAP was specifically knocked out in dopaminergic neurons." (PMID 40801564, 2025). "Interestingly, cingulate-PSAP-deficient mice presented normal locomotion, a non-depressive state, and an intact working memory, but suffered from increased anxiety, and, more importantly, impaired sensorimotor gating." (PMID 36233357, 2022). "However, PSAP levels failed to correlate with non-motor symptom scores obtained with the depression rating scales BDI-II, MADRS-S, HADS-D, the anxiety rating scale HADS-A, and the fatigue rating scale MFS." (PMID 37726325, 2023).
depression (3 papers, 2022 to 2025). "Given these premises, we examined the protein levels of PSAP and PGRN in postmortem cingulate cortex tissue from healthy controls and schizophrenia patients, using bipolar disorder and major depressive disorder as disease controls." (PMID 36233357, 2022). "PSAP, PGRN, and β-actin protein levels were quantified by Western blotting analysis in postmortem cingulate cortex tissue from healthy controls and patients suffering from schizophrenia, bipolar disorder, or major depressive disorder." (PMID 36233357, 2022). "To further clarify the role of PSAP and PGRN in schizophrenia, we examined PSAP and PGRN levels in postmortem cingulate cortex tissue from healthy controls along with patients who had suffered from schizophrenia, bipolar disorder, or major depressive disorder." (PMID 36233357, 2022). "Interestingly, significantly decreased PSAP levels were found exclusively in schizophrenia patients compared with healthy controls, but not in patients with bipolar disorder or major depressive disorder." (PMID 36233357, 2022). "Consistent with the genetic studies, we report that PSAP and PGRN are decreased in the cingulate cortex of patients with schizophrenia, but not in patients with bipolar disorder or depression." (PMID 36233357, 2022).
metastatic tumor (3 papers, 2010 to 2025). "Moreover, we have demonstrated that stimulation of Tsp-1 via ectopic expression of PSAP and systemic delivery of a therapeutic peptide derived from PSAP potently inhibits primary and metastatic tumor growth in multiple tumor models." (PMID 36575174, 2022). "We have previously identified a tumor-secreted protein, prosaposin, (PSAP) that functions as a paracrine inhibitor of primary and metastatic tumor growth." (PMID 36575174, 2022).
ovarian carcinoma (3 papers, 2010 to 2025). A malignant neoplasm originating from the surface ovarian epithelium. "Therapeutically, targeting PSAP holds promise: a cyclic PSAP-derived peptide reactivates anti-tumor TSP-1/CD36 signaling to inhibit ovarian cancer growth and metastasis in vivo." (PMID 40801564, 2025). "The prognostics relevance of PSAP has been demonstrated for ovarian cancer, while spMOCA enabled us to generalize PSAP’s prognostics value to breast and non-small cell lung cancers, where these broader relevance are supported by previous studies." (PMID 41370198, 2025). "Another study showed that in breast and ovarian cancer cell lines from human, there is specific mannose-6-phosphate (M6P) receptor-independent interaction between procathepsin D (proCath-D) and PSAP, occurring in both the intracellular space and secretory media." (PMID 40801564, 2025).